STAT1 (signal transducer and activator of transcription 1)
Diseases named in the same sentence as STAT1 in open-access papers (continued):
Sharing a sentence is not in itself a finding about the gene and the disease.
Obesity (continued). "Specifically, we detected down-regulation of HLA-DRA (1.38-fold), STAT1 (1.3-fold), TNFSF10 (1.7-fold), and FCGR3A (fold reduction 1.65) with pregravid obesity." (PMID 34195568, 2021). "For example, obesity-induced oxidative stress plays a critical role in T cell protein tyrosine phosphatase (TCPTP) inactivation, leading to interference in STAT-1 and STAT-3 signal transduction and the development of NASH to HCC." (PMID 34583662, 2021). "The oxidative hepatic environment in obesity inhibits the STAT1 and STAT3 phosphatase, T cell protein tyro-sine phosphatase (TCPTP), which results in increased STAT1 and STAT3 signaling." (PMID 32660130, 2020). "In a mouse model with obesity, researchers found that obesity triggered the development of NASH through the activation of STAT1 signal transduction, while the inhibition of this STAT1 could improve NASH." (PMID 38540097, 2024). "Obesity-related oxidative stress leads to the recruitment of T cells accompanying NASH, fibrosis along with HCC through inactivation of STAT-1 and STAT-3 phosphatase T cell protein tyrosine phosphatase (TCPTP) and activation of STAT-1 and STAT-3 signaling." (PMID 36457551, 2022). "Whilst macrophage STAT1 has not been reported to play a role in obesity or insulin resistance; in vitro and ex vivo studies demonstrated that STAT1 is activated in response to high glucose where a large epigenetic component is attributed to its function." (PMID 32785109, 2020). "The NF-κB target genes IRF1, STAT1, JUN, HSP90AA1, FOS, and EGR1, were enriched in the pathway of Glucocorticoid receptor regulatory network and homeostasis pointing towards their critical role in obesity." (PMID 31013288, 2019). "Importantly, they identified STAT3 as the driver of HCC progression in obesity, whereas obesity-driven NASH and fibrosis depend on STAT1." (PMID 30591653, 2018).
asthma (44 papers, 2006 to 2026). "Evidence exhibiting the cross-talk association of Stat1 with the NF-kB pathway in OVA-induced asthma and how mogroside V treated the cells should be further investigated." (PMID 35371026, 2022). "Activation of MAPK/STAT1 has been noted to be implicated in the inflammation and airway remodeling in asthma 37,38." (PMID 33994863, 2021). "Previous studies have shown that the transcriptional role of STAT1 in asthma appears to be associated with corticosteroid insensitivity and Th1 bias." (PMID 33902571, 2021). "It is well known that the AKT-MAPK-ATF2 or STAT1 signaling pathways are implicated in YKL-40 expression or exacerbation of asthma symptoms." (PMID 25056157, 2014). "At the cellular level, mTOR can physically interact with NF-κappaB or STAT1, both of which are associated with airway inflammation in asthma." (PMID 22685525, 2012). "Further, we queried the TRANSFAC database for transcription factor binding sites which include rs510432 and identified two transcription factors, STAT1 and C-Fos, which have been associated with asthma." (PMID 22536318, 2012). "When we queried the TRANSFAC database for transcription factor binding sites that include rs510432, we identified two transcription factors, STAT1 and C-Fos, which have been associated with asthma and may be mediating the functional differences observed." (PMID 22536318, 2012). "Recent systems biology analyses identified four potential molecular triggers—AKT1, MAPK13, STAT1, and TLR4—as candidate regulators of asthma-associated signaling pathways." (PMID 40650018, 2025). "Very recently it has been described that IL-9 induction was restrained by IFN-γ/STAT1 and IL-10, pointing to a new role of this pathway in the modulation of asthma disease." (PMID 40650018, 2025). "The administration of IL-27 via intranasal route has been shown to mitigate Th2-mediated allergic lung inflammation and restructuring in murine asthma models through the restoration of both STAT1 and STAT3 signaling pathways." (PMID 39062111, 2024). "In the ovalbumin (OVA)-elicited asthmatic rat model, M2 macrophage exosome miR-370 lowers FGF1 expression and down-regulates the MAPK/STAT1 signaling pathway to alleviate lung tissue fibrosis and inflammation, thus ameliorating asthma." (PMID 37142272, 2023). "The STAT1 signaling pathway is thought to regulate several immune‐mediated diseases, including asthma, by inducing proinflammatory subgroups." (PMID 37249291, 2023). "Previous studies reported that M2Φ-Exos carried miR-370 to inhibit inflammation and alleviate asthma progression by regulating the FGF1/MAPK/STAT1 axis." (PMID 35500231, 2022). "Further, we tested the effect of targeting STAT1 on asthma exacerbation by using Fludarabine, a pharmaceutical drug that decreases the activation of STAT1 and is currently used clinically to treat certain cancers." (PMID 35280986, 2022). "A recent study reported that M2 macrophage-derived exosomes (M2Φ-Exos) carried miR-370 to mitigate asthma progression via restraining the FGF1/MAPK/STAT1 signaling axis." (PMID 35500231, 2022). "AHR and ASM mass, both key features of asthma, were corticosteroid insensitive in both WT and Stat1−/− mice." (PMID 34755542, 2021). "Given the potential role for Th1 inflammation in severe asthma, it is important to understand the role of STAT1 in the context of corticosteroid sensitivity." (PMID 34755542, 2021). "There was also a trend toward reduced STAT1 phosphorylation after administration of DCs in mice with OVA-induced asthma." (PMID 32807859, 2020). "STAT1 is critical to the antimicrobial immune response, but overactivation of STAT1 is a contributor to several inflammatory diseases such as asthma, celiac disease, and ulcerative colitis (70, –, 72)." (PMID 33328346, 2020). "Subjects with asthma and multiple AETRIs display a pro-inflammatory signature at baseline, associated with elevated STAT, IL-15 and ISGs, and an impaired STAT1 response during acute asthma exacerbations." (PMID 29486764, 2018).
asthma (continued). "In an animal model of asthma a single application of this STAT1 decoy oligonucleotides significantly reduces airway hyperresponsiveness, the number of BAL eosinophils and lymphocytes and the BAL level of IL-5." (PMID 18315837, 2008). "Many transcription factors (for example NF-κB, AP-1, GATA-3, STAT-1 STAT-6, c-Maf, NFATs and SOCS) have been implicated in the differentiation of Th2 lymphocytes and therefore represent therapeutic targets for asthma." (PMID 18315837, 2008). "The data above indicate that upregulated airway CSF1 may be involved in the airway inflammation of asthma by interacting with its receptor and activating the STAT1 protein." (PMID 37249291, 2023). "STAT1 activity is increased in some inflammatory diseases, such as asthma and rheumatoid arthritis." (PMID 34112215, 2021). "Rhinovirus infection of epithelial cells increases STAT1 expression, and increases in STAT1 activity may be more prominent during viral induced exacerbations of asthma." (PMID 27716212, 2016). "RSV infection also induces STAT1-dependent IFNγ production by NK cells, while STAT1-deficient mice exhibit increased IL-5+ and IL-13 + ILC2s and IL-17A + ILC3s in the lung in response to RSV infection, suggesting that ILCs play a role in RSV infection beyond impacting asthma pathology." (PMID 38684766, 2024). "Thus, we presumed that CSF1‐CSF1R is associated with airway eosinophil inflammation might via activating the STAT1 signaling in asthma." (PMID 37249291, 2023). "Taken together, this study describes the proteomic profile underpinning molecular mechanisms of FLU-induced asthma exacerbation and identifies STAT1 as a potential therapeutic target, more importantly, we provided a novel therapeutic strategy that may be clinically translated into practice." (PMID 35280986, 2022). "Furthermore, we investigated the effects of preventive and therapeutic IL-27 administration on the allergic airway inflammation in ovalbumin (OVA)-induced asthma mouse models and studied whether the effect is related to the STAT1 and GADD45γ/p38 MAPK pathways." (PMID 27687913, 2016). "Gene and protein expression of the four potential asthma triggers, AKT1, MAPK13, STAT1, and TLR4, was analyzed in PBMC samples obtained from AA, NA, and HC." (PMID 40650018, 2025). "Here, we have analyzed theoretical signaling pathways related to four asthma trigger proteins, AKT1, MAPK13, STAT1, and TLR4, defined by previous systems biology study as proteins able to modify the activation of many effector proteins of respiratory diseases." (PMID 40650018, 2025). "A mouse model of asthma induced by ovalbumin and miR-370 carried by M2 macrophage-derived exosomes alleviated asthma progression by inhibiting the FGF1 and MAPK/STAT1 signaling pathways." (PMID 35884901, 2022). "There was concordance of gene over- (STAT1, XBP1) and underexpression (NELF, RARA) in asthma and Crohn’s disease ileum when our results were compared to another dataset (p = 3.66 × 10–7)." (PMID 34332619, 2021). "Collectively, we conclude that M2Φ-Exos carry miR-370 to alleviate asthma progression through downregulating FGF1 expression and the MAPK/STAT1 signaling pathway." (PMID 33994863, 2021). "This study shows that subjects with asthma and multiple AETRIs exhibit a pro-inflammatory PBMC transcriptome at baseline characterized by abnormalities in STAT1 and IL-15 and a dysregulated transcriptional profile during asthma exacerbations." (PMID 29486764, 2018). "In particular, when STAT1, STAT3, and STAT6 are activated as transcription factors by inflammatory cytokines, they can induce the expressions of genes and lead to inflammatory conditions such as asthma, rheumatoid arthritis, and AD." (PMID 38258052, 2023).
asthma (continued). "The observed increase of JAK1 expression in unstimulated cells, combined with a prominent role for STAT1 in steroid and poly I:C responses, suggests that the JAK1-STAT1 pathway holds clues to the complex interaction between asthma, therapeutic response to steroids, and antiviral responses." (PMID 33902571, 2021). "The STAT1 and STAT4 pathways are considered vital for Th1 differentiation, while the IL-4/IL-13/STAT-6 pathway has been confirmed to be the major modulator of Th2 differentiation in asthma pathophysiology." (PMID 34093516, 2021). "All of the results suggested that the inflammation existing in the asthma model mainly impaired the phosphorylation of the STAT1 protein, which resulted in the impairment of the STAT1 pathway, and had no obvious effect on the GADD45γ/p38 MAPK pathway." (PMID 27687913, 2016). "In the asthma group, the phosphorylation of STAT1 was impaired, while GADD45γ and p38 MAPK exhibited no obvious changes." (PMID 27687913, 2016). "In the asthma group, the phosphorylation level of STAT1 was significantly impaired, while p38 MAPK exhibited no obvious changes (there was a slight up-regulation)." (PMID 27687913, 2016). "We found that the inflammation existing in the asthma model mainly impaired the phosphorylation of the STAT1 protein, which resulted in the impairment of the STAT1 pathway, and had no obvious effect on the GADD45γ/p38 MAPK pathway." (PMID 27687913, 2016). "In contrast, the low-dose preventative administration of IL-27 with multiple administrations could either reverse the impairment of the STAT1 pathway or strengthen the GADD45γ/p38 MAPK pathway and improve the pathologic symptoms of asthma." (PMID 27687913, 2016). "This flavonoid also inhibited the activation of NF-κB and STAT-1 in macrophages, and reduced inflammatory cytokines including; TNF-α, IL-6, IL-1β and PGE2 and also increased inflammatory cytokines in vitro, which it can useful for the treatment of allergic disorders such as asthma." (PMID 33295229, 2020). "In conclusion, this study supports the potential involvement of AKT1, MAPK13, STAT1, and TLR4 in asthma pathogenesis and highlights differences between allergic and nonallergic asthma at the molecular level." (PMID 40650018, 2025).
influenza (44 papers, 2011 to 2026). An acute viral infection of the respiratory tract, occurring in isolated cases, in epidemics, or in pandemics; it is caused by serologically different strains of viruses (influenzaviruses) designated A, B, and C, has a 3-day incubation period, and usually lasts for 3 to 10 days. "We adoptively transferred WT or STAT1-deficient γδ T cells into WT mice following primary influenza infection, and then mice were challenged with secondary pneumococcal infection." (PMID 24408967, 2014). "Next, we conducted an MRI scan measuring the LVEF, circumferential, and longitudinal strain from WT and Stat1−/− mice infected with influenza." (PMID 38750107, 2024). "We further measured the Lcn2 protein levels and found the levels were increased in the hearts of influenza-infected Stat1−/− mice when compared to influenza-infected WT mice." (PMID 38750107, 2024). "We found that there was a significantly higher frequency of CD45+ CD11b+ Ly6G+ neutrophils present in the hearts of STAT1−/− mice infected with influenza compared to the WT control mice." (PMID 38750107, 2024). "Overall, our data suggest that Stat1 suppresses the neutrophilic infiltration and the induction of Lcn2 thereby suppressing the Lcn2-mediated pathological effects during influenza-induced myocarditis." (PMID 38750107, 2024). "We infected both C57BL/6 and STAT1−/− mice with influenza or PBS control and then measured the relative expression of Mx1 and the chemokine CXCL10." (PMID 38750107, 2024). "After discovering STAT1 is highly expressed in the hearts of influenza-infected mice, we decided to investigate the role of STAT1 in the pathogenesis of myocarditis." (PMID 38750107, 2024). "Conversely, compounds effectively treated allergic rhinitis and influenza through inhibiting STAT1 signaling, reducing the expression of inflammatory mediators, and regulating cell differentiation." (PMID 36324680, 2022). "To address the regulation of the IFN pathway by Tpl2 in response to influenza infection, we first measured the expression of both STAT1 and SOCS1, which serve as positive and negative regulators of the IFN pathway, respectively." (PMID 34691044, 2021). "SOCS1 is an ISG induced during influenza infection to inhibit the expression of IFNs and their downstream signaling by inhibiting STAT1 or JAK1, which are required for signaling via this pathway." (PMID 34691044, 2021). "We have shown that type I IFN and STAT1 inhibit the S. aureus-induced Type 17 response, thereby decreasing bacterial clearance during influenza-bacterial super-infection." (PMID 31159430, 2019). "Our study showing that the Nlrp3 inflammasome contributes to lethality upon gastrointestinal MNV infection in IFN-unresponsive Stat1-/- mice is in line with this observation in Influenza-infected mice." (PMID 31017981, 2019). "As expected, we found increased STAT1 expression in Stat2−/− mice when compared to WT mice during influenza-bacterial super-infection." (PMID 30337919, 2018). "We have recently shown that STAT1 is involved in increasing bacterial burden through suppression of the Type 17 immune response during influenza-bacterial super-infection." (PMID 30337919, 2018). "For this experiment, we transferred CD45.2+ splenocytes from IFNAR+/− or IFNAR−/− donor mice into B6 WT hosts (CD45.1+), followed by infection with influenza, and phosphorylation analysis of STAT1." (PMID 23300570, 2012). "The finding that Signal Transducer and Activator of Transcription 1 (STAT1) suppresses neutrophil recruitment during influenza-fungal co-infections, along with the issue of chemotherapy-induced “neutrophil resonance,” highlights the need for timely interventions." (PMID 41141324, 2025). "A unique signature of lncRNA expression was reported in both SARS and influenza infection in in vitro murine studies, suggesting a role of lncRNAs in the regulation of the innate immune response and pathogenesis through the Signal Transducer and Activator of Transcription 1 (STAT1)." (PMID 40149464, 2025).
influenza (continued). "Here, we have investigated the role of anti-viral STAT1 signaling in influenza-induced myocarditis." (PMID 38750107, 2024). "We further investigated the role of STAT1 in influenza-induced myocarditis." (PMID 38750107, 2024). "Further, we analyzed the role of Stat1 in the heart during influenza infection." (PMID 38750107, 2024). "Hence, production of factors such as STAT1 by the hNECs is also crucial in ensuring appropriate regulation of IFNγ-mediated expression of influenza response genes to modulate inflammation and to minimize damage." (PMID 31461941, 2019). "We recently found a lack of or a small fold viral titer change in STAT1 or STAT2 gene deficient mice infected with influenza infection." (PMID 31159430, 2019). "Next, we determined whether STAT1 is altered due to increased levels of IFNγ in Stat2−/− mice during influenza-bacterial super-infection." (PMID 30337919, 2018). "Importantly, this defect was further exaggerated in Stat1—/—mice, suggesting a synergistic function of type I and II IFNs in suppressing neutrophil recruitment during influenza infection." (PMID 26731100, 2016). "In conclusion, comparison between wt, IFNαβR−/− and STAT1−/− genotypes in a high IFN producer genetic background such as 129 allowed us to unmask the pathogenic potential of IFNαβ and its nonredundant role in causing excessive inflammation in response to influenza infection." (PMID 24844667, 2014). "We found increased expression of influenza M protein, Stat1, Oasl2, and CCL2 in influenza-infected mice when compared to PBS-treated controls." (PMID 38750107, 2024). "Further, our data suggest that STAT1 suppresses neutrophilic infiltration and the induction of Lcn2 in the heart, and Lcn2 affects the LVEF in influenza-induced myocarditis." (PMID 38750107, 2024). "In contrast, influenza patients showed activation of STAT3 and nuclear factor kappa-light-chain enhancers of activated B-cells (NF-kappa-beta) pathways instead of STAT1/IRF3." (PMID 38542251, 2024). "We observed increased expression of Stat1, Stat2, Mx1, Oasl2, CCL2, CCL3, CXCL9, and CXCL10 in influenza-infected hearts and lungs when compared to PBS-treated controls." (PMID 38750107, 2024). "Therefore, we determined whether STAT1 affects Lcn2 expression in influenza-induced myocarditis." (PMID 38750107, 2024). "Empagliflozin treatment decreased the expression of the inflammatory cytokines IL-1β, IL-6, and CCL2; the percentage of inflammatory monocytes and inducible NO synthase–positive macrophages; and IFN response genes Stat1 and CXCL9 during influenza infection." (PMID 38112660, 2023). "Several studies, mainly in mouse models, have demonstrated that blocking the IFNAR receptor leads to high influenza viral loads, high mortality and decreased activation of ISGs such as PKR and Signal transducer and activator of transcription 1 (Stat1)." (PMID 35056582, 2022). "These flavonoids activate type I IFN secretion and protect against influenza by increasing interferon-α/β receptor (IFNAR) and signal transducer and activator of transcription 1 (STAT1) signaling." (PMID 33925715, 2021). "STAT1, TAP1, PSMB9, and PSME2, which are up-regulated preferentially by IFN-γ, were overexpressed only in influenza-specific cluster 1 (blue)." (PMID 32651212, 2020). "Our study further indicated that rosiglitazone treatment decreased downstream signaling agents STAT1, STAT2, and the ISGs Mx1, CXCL9 and CXCL10 during influenza infection." (PMID 31159430, 2019). "The comparison of the KEGG “Influenza” response pathway led to the identification of nodes targeted by C. burnetii and B. abortus to down-modulate TLR4/TLR3, STAT1 and type I IFN-responsive genes." (PMID 24915541, 2014). "As expected, epithelia of all genotypes showed influenza-induced upregulation of genes such as IFNλ (IL28), which are upstream of IFN-mediated STAT1 induction." (PMID 24844667, 2014).